FMN2 (formin 2)
Description:
Actin-binding protein that is involved in actin cytoskeleton assembly and reorganization. Acts as an actin nucleation factor and promotes assembly of actin filaments together with SPIRE1 and SPIRE2. Involved in intracellular vesicle transport along actin fibers, providing a novel link between actin cytoskeleton dynamics and intracellular transport (By similarity). Required for asymmetric spindle positioning, asymmetric oocyte division and polar body extrusion during female germ cell meiosis (By similarity). Plays a role in responses to DNA damage, cellular stress and hypoxia by protecting CDKN1A against degradation, and thereby plays a role in stress-induced cell cycle arrest. Also acts in the nucleus: together with SPIRE1 and SPIRE2, promotes assembly of nuclear actin filaments in response to DNA damage in order to facilitate movement of chromatin and repair factors after DNA damage. Protects cells against apoptosis by protecting CDKN1A against degradation.
Tractability: Antibody: its Gene Ontology location is reachable by antibodies, with high confidence; UniProt places it where antibodies can reach, with medium confidence. PROTAC: its protein half-life has been measured.
Gene: Protein-coding gene on chromosome 1 (240,014,348 to 240,475,187, forward strand). Ensembl gene ENSG00000155816.
Subcellular location: Cytoplasm, cytoskeleton; Cytoplasm, cytosol; Cytoplasm, perinuclear region; Nucleus; Nucleus, nucleolus; Cell membrane; Cytoplasmic vesicle membrane; Cytoplasm, cell cortex
Subcellular location (Human Protein Atlas): Actin filaments; Plasma membrane
Gene Ontology:
Molecular function: actin binding; microtubule binding
Biological process: actin cytoskeleton organization; cell migration; cellular response to hypoxia; DNA damage response; formin-nucleated actin cable assembly; negative regulation of apoptotic process; negative regulation of protein catabolic process; positive regulation of double-strand break repair; establishment of meiotic spindle localization; homologous chromosome movement towards spindle pole in meiosis I anaphase; intracellular transport; oogenesis; polar body extrusion after meiotic divisions; vesicle-mediated transport; intracellular signal transduction
Cellular component: actin cytoskeleton; cytosol; nucleolus; nucleus; cell cortex; cytoplasmic vesicle membrane; endoplasmic reticulum; endoplasmic reticulum membrane; microtubule cytoskeleton; plasma membrane; cytoplasm; cytoskeleton; microvillus; perinuclear region of cytoplasm; spindle
Genetic constraint (gnomAD): Loss-of-function variants: 49 observed, 121.96 expected, observed/expected ratio (o/e) 0.4, 90% interval 0.32 to 0.51. The upper end of that interval is the gene's LOEUF score, 0.51, which puts it in group 2 of 6, group 1 being the genes least tolerant of losing a copy. Missense variants: 1,785 observed, 1,753.6 expected, observed/expected ratio (o/e) 1.02, 90% interval 0.98 to 1.06. Synonymous variants: 817 observed, 725.14 expected, observed/expected ratio (o/e) 1.13, 90% interval 1.06 to 1.19.
Homologues: Orthologues: macaque FMN2 (86% identical), rabbit FMN2 (79% identical), rat Fmn2 (74% identical), mouse Fmn2 (74% identical), pig FMN2 (70% identical), tropical clawed frog fmn2 (44% identical), Caenorhabditis elegans daam-1 (9% identical), Drosophila melanogaster form3 (9% identical), Caenorhabditis elegans fhod-1 (8% identical). Paralogues in human: INF2 (14% identical), DIAPH1 (13% identical), GRID2IP (12% identical), DAAM1 (11% identical), FMNL2 (11% identical), FMNL1 (11% identical), DAAM2 (11% identical), DIAPH2 (10% identical), DIAPH3 (10% identical), FHOD3 (10% identical), FMNL3 (10% identical), FHOD1 (8% identical), and 6 more.
Diseases named in the same sentence as FMN2 in open-access papers:
FMN2 is named in the same sentence as 45 diseases in open-access papers, as found by Europe PMC text mining. Sharing a sentence is not in itself a finding about the gene and the disease. The quoted sentences say what the papers report.
Intellectual disability (5 papers, 2017 to 2022). "Previous research reported mental retardation cases with FMN2 nonsense or truncation mutations on different sites." (PMID 35227295, 2022). "Mutations of other formin genes in addition to DIAPH1 and FMN2 have been associated with intellectual disability." (PMID 34685534, 2021). "Recent studies have implicated Fmn2 in neurodevelopmental disorders, including sensory processing dysfunction and intellectual disability in humans." (PMID 34193512, 2021). "In addition, FMN2 has been linked to synapse formation and deletion mutations of the Fmn2 gene are associated with intellectual disability, pointing to a role for Fmn2 in memory function in mice and humans." (PMID 28768717, 2017). "A few cases of intellectual disability denominated mental retardation, autosomal recessive 47 (MRT47, MIM: 616193), are produced by mutations of FMN2." (PMID 34685534, 2021). "Mutations of DIAPH1, FMN2, and INF2 are associated, to varying degrees, with intellectual disability and neurodevelopmental disorders." (PMID 34685534, 2021).
melanoma (5 papers, 2007 to 2024). A malignant, usually aggressive tumor composed of atypical, neoplastic melanocytes. "For example, FMN2 RNA is reported to be overexpressed in certain breast cancers and melanomas but underexpressed in certain renal cancers (oncomine)." (PMID 23375502, 2013). "Our melanoma invasion signature is associated with upregulation of critical NF-κB effectors including CXCL1, FMN2, MMP1, IL-8, IGFBP3 which have been implicated in the regulation of tumor cell proliferation, motility, migration, and/or invasion." (PMID 17611626, 2007).
microcephaly (5 papers, 2017 to 2025). A congenital or acquired developmental disorder in which the circumference of the head is smaller than normal for the person's age and sex. "We have previously shown that actin-binding Filamin A (FlnA) and actin-nucleating Formin 2 (Fmn2) influence the development of the brain causing microcephaly in mice." (PMID 29240780, 2017). "As seen in the brain where loss of FlnA and Fmn2 leads to microcephaly due to impaired neural progenitor proliferation, a similar decrease in cell proliferation rates is observed in the thoracic wall and contributes to the phenotype." (PMID 29240780, 2017). "Loss of both FlnA and Fmn2 result in impaired canonical Wnt signaling within neural progenitors by disrupting the trafficking of the Lrp6 receptor, thereby causing microcephaly (small brain)." (PMID 29240780, 2017). "Other reports implicate Fmn2 mutations in corpus callosum agenesis and microcephaly." (PMID 34193512, 2021). "In cones, several genes associated with cell migration (LARGE1), mechanistic target of rapamycin (mTOR) signaling (RICTOR), microcephaly (XRCC4), and intellectual developmental disorder (FMN2) were strongly dysregulated." (PMID 40706588, 2025).
colorectal cancer (4 papers, 2021 to 2024). A primary or metastatic malignant neoplasm that affects the colon or rectum. "The frequency of FMN2 mutations markedly differs between the stages of colorectal cancer." (PMID 34685534, 2021). "Moreover, the dysregulation of FMN2 is identified in large cohort of colorectal cancer patients, and could serve as early diagnostic marker of colorectal cancer." (PMID 34061869, 2021). "ABCC1 and FMN2 were host genes of exosomal circRNA that were differentially expressed by more than two-fold in colorectal cancer." (PMID 34249673, 2021). "Another example is the downregulation of FMN2 expression by hypermethylation of its promoter during the early stages of colorectal cancer progression, possibly contributing to the initial steps of cancer development." (PMID 34685534, 2021). "Circular RNA of FMN2 has been reported to play a role in colorectal cancer." (PMID 38671536, 2024).
memory impairment (3 papers, 2017 to 2021). "Consistent with this idea, it was observed that old Fmn2 KO mice were more likely to show early age-associative memory impairment compared with age-matched controls, suggesting that reduced FMN2 levels contribute to age-related memory impairment." (PMID 34685534, 2021). "Thus, we reasoned that the analysis in 3‐month‐old mice would enable us to detect synergistic effects on memory impairment in Fmn2−/− and APPPS1‐21 mice." (PMID 28768717, 2017). "In line with our initial observation, Fmn2−/− mice did not exhibit memory impairment at 3 months of age." (PMID 28768717, 2017).
Alzheimer disease (2 papers, 2017 to 2021). A progressive, neurodegenerative disease characterized by loss of function and death of nerve cells in several areas of the brain leading to loss of cognitive function such as memory and language. "We show that the actin nucleator Formin 2 (Fmn2) is deregulated in PTSD and in Alzheimer's disease (AD) patients." (PMID 28768717, 2017).
breast carcinoma (2 papers, 2013 to 2021). "FLG2, FMN2, and ERBB3 have been reported to be related to breast cancer." (PMID 35111673, 2021).
dementia (2 papers, 2017 to 2022). Loss of intellectual abilities interfering with an individual's social and occupational functions. "Next, we decided to explore the mechanisms by which FMN2‐mediated phenotypes at a young age increase risk for late life dementia." (PMID 28768717, 2017). "Fmn2 is related to cell cycle arrest, DNA damage against stress conditions, and the pathogenesis of neuropsychiatric disorders and dementia." (PMID 36614117, 2022). "Our data also provide a more general insight of how the various AD risk factors (in our case, FMN2‐mediated PTSD‐like phenotypes, amyloid deposition, and aging) contribute to dementia." (PMID 28768717, 2017).
hepatocellular carcinoma (2 papers, 2021 to 2022). A malignant tumor that arises from hepatocytes.
amyloid (1 paper, 2017). "Loss of Fmn2 accelerates age‐associated memory decline, which is further accelerated in the presence of amyloid pathology and is accompanied by deregulation of hippocampal gene expression." (PMID 28768717, 2017). "Indeed, we observed neglectable changes in hippocampal gene expression in 3‐month‐old Fmn2−/− mice, while loss of Fmn2 dramatically increases the number of deregulated genes during aging or in response to amyloid pathology." (PMID 28768717, 2017).
Anxiety (1 paper, 2017). Intense feelings of nervousness, tension, or panic often arise in response to interpersonal stresses. "Although gross brain morphology, motor coordination, explorative behavior, and basal anxiety were similar when comparing 3‐month‐old Fmn2−/− mice and control littermates (Fig EV2), our Fmn2−/− mice constitutively lack FMN2." (PMID 28768717, 2017).
autism (1 paper, 2023). Persistent deficits in social interaction and communication and interaction as well as a markedly restricted repertoire of activity and interest as well as repetitive patterns of behavior. "Interestingly, many of the up-regulated genes are involved in mental conditions and higher cognitive functions, including the schizophrenia- and autism-associated gene SYN2 and cognition- and intelligence-associated genes FMN2, CTNND2, and CACNA1A 67–71." (PMID 36788214, 2023).
bladder cancer (1 paper, 2020).
Cantrell syndrome (1 paper, 2017). "We observed defects in rib and sternum midline closure leading to thoracoabdominal schisis in FlnA+Fmn2 knockout mice, reminiscent of the pentalogy of Cantrell syndrome." (PMID 29240780, 2017).
cognitive decline (1 paper, 2017). "Next we decided to investigate the impact of FMN2 on cognitive decline in the presence of another risk factor for AD, namely amyloid deposition." (PMID 28768717, 2017).
coronary heart disease (1 paper, 2013). "However, a genetic variant within FMN2 has been associated with coronary heart disease." (PMID 23437003, 2013).
Hydrocephalus (1 paper, 2021). Hydrocephalus is an active distension of the ventricular system of the brain resulting from inadequate passage of CSF from its point of production within the cerebral ventricles to its point of absorption into the systemic circulation. "Five genes (TRIM71, SMARCC1, PTEN, PIK3C, MTOR) were found to be involved in syndromic forms of hydrocephalus, and three other genes (FMN2, FOXJ1 and PTCH1) to be responsible for severe hydrocephalus with AS stenosis." (PMID 34092257, 2021).
Infertility (1 paper, 2015). "Mutations in the Fmn2 gene cause infertility in mouse and humans and knockout of Fmn2 causes spindle migration failure and impairs the formation of the cytoplasmic actin mesh in oocytes, which is essential for the completion of meiosis I." (PMID 25837661, 2015).
leukemia (1 paper, 2013). A malignant (clonal) hematologic disorder, involving hematopoietic stem cells and characterized by the presence of primitive or atypical myeloid or lymphoid cells in the bone marrow and the blood. "More recently, FMN2 was also reported as a potential oncogene in leukemia." (PMID 23375502, 2013).
medullary thyroid carcinoma (1 paper, 2022). "CNV loss on the FMN2 gene promotes lymph node metastasis in medullary thyroid carcinoma family." (PMID 35642209, 2022).
Micro syndrome (1 paper, 2022). "But interestingly, FMN2 and RGS7 deletion was discovered in Warburg–Micro Syndrome patients." (PMID 36192753, 2022).
ovarian dysgenesis (1 paper, 2022). "However, to confirm the pathogenicity of these variants and the relationship between FMN2 and ovarian dysgenesis in humans, further study with large samples size is requisite." (PMID 35227295, 2022).
peripheral nerve injury (1 paper, 2024). Injury to a peripheral nerve. "Next, by sequencing and in silico drug screen of fmn2 knockdown, small-molecule metaxalone has been discovered to be a regulator of microtubule dynamics and a novel therapeutic drug for the treatment of peripheral nerve injury." (PMID 39415832, 2024).
tumor (12 papers, 2007 to 2025). "In the TWM cases, except case 1, ARID3A, ASXL1, ASXL2, FMN2, FAM83B and ZFHX4 mutations were also identified as potential oncogenic drivers, known from other tumor types." (PMID 36980598, 2023). "We analyzed the effect of p14ARF induction on nucleolar protein dynamics using SILAC mass spectrometry and have identified the human Formin-2 (FMN2) protein as a component of the p14ARF tumor suppressor pathway." (PMID 23375502, 2013). "The expression of FMN2 is predominantly observed in tumor suppressor pathway." (PMID 34061869, 2021). "In contrast, mutant BRAF, ATM, LRP1B, FAT4, FMN2, TRRAP, and ROS1 had higher stromal score (except ATM), immune score and ESTIMATE score, and the tumor purity was lower than the wild-type." (PMID 33836681, 2021). "While EDNRB and FMN2 as well as TBXT and ZNF671 could have potential tumor suppressor functions, MOS is a well-known oncogene." (PMID 38643219, 2024). "Additionally, p21 expression can be further increased by the Formin-2 (FMN2) protein, which is a component in the p14ARF tumour suppressor pathway." (PMID 34062959, 2021). "The contribution of the formin family genes to cancer progression and metastasis has recently begun to emerge and here we demonstrate for the first time the ability of FMN2 and DAAM2 to regulate tumour cell migration and invasion, using siRNA-mediated inhibition of each of these formin genes." (PMID 24223803, 2013).
cancer (11 papers, 2013 to 2025). A tumor composed of atypical neoplastic, often pleomorphic cells that invade other tissues. "Genistein has been suggested to inhibit metastasis of cancer cells by inhibiting cell signaling and the redistribution of actin-binding proteins such as formin-2 and profilin." (PMID 23782904, 2013). "Increased FMN2 expression has also been shown to promote cancer cell migration and invasion." (PMID 40424447, 2025). "In addition to known cancer-associated variants, we identified P/LP variants in the novel candidate cancer genes SF3B4, FMN2, and MMP13 (class 4)." (PMID 37377903, 2023). "MiR-144 by targeting FMN2 could regulate cancer cell proliferation and G1/S transition." (PMID 33330110, 2020). "Together with FMN2, PCLO formed a positive feedback in the evolutionary tree in stage IV, suggesting their roles in accelerating cancer evolution." (PMID 29463849, 2018). "Ten patients had germline mutations affecting cancer predisposition genes not typically linked to WT: CHEK2 in 4 children, and BLM, BRCA2, CDKN2A, FMN2, PIK3C3, and STK11 in one patient each." (PMID 40340749, 2025). "Unlike fibroblasts, where a perinuclear actin cap and formin FMN2 have been proposed to regulate cell migration and nuclear shape, carcinoma cells used in this study do not rely on perinuclear actin cap or FMN2 for cell motility." (PMID 34205257, 2021). "E2F1 and NF-κB proteins are often deregulated in cancer and could account for the lack of FMN2 expression observed in certain cancer types." (PMID 23375502, 2013). "Interestingly, this response was also observed in the absence of ARF induction, indicating that FMN2 is required for suppression of apoptosis and hence survival of cancer cells." (PMID 23375502, 2013).
neurodevelopmental disorder (3 papers, 2018 to 2024). A behavioral and cognitive disorder with onset during the developmental period that involves impaired or aberrant development of intellectual, motor, or social functions. "FMN2, a member of the Formin family implicated in multiple neurodevelopmental disorders, is an actin-binding protein that regulates actin networks and cell polarity and is essential for meiotic metaphase." (PMID 38643219, 2024). "Our findings underscore the importance of Fmn2 in neural development across vertebrate lineages and highlight zebrafish models in understanding neurodevelopmental disorders." (PMID 34193512, 2021). "Of the children with SPD, 2/11 (18%), were identified as having a de novo loss of function or missense mutation in genes previously reported as causative for neurodevelopmental disorders (MBD5 and FMN2)." (PMID 29801487, 2018).
FMN2 also shares sentences with these, for which no sentence is quoted: cardiomyopathy (1 paper); female infertility (1); genetic diseases (1); glioblastoma (1); hearing loss (1); Insulin resistance (1); lung carcinoma (1); neuroblastoma (1); Obesity (1); peripheral neuropathy (1); posttraumatic stress disorder (1); Premature ovarian insufficiency (1); primary ovarian insufficiency (1); prostate carcinoma (1); renal carcinoma (1); renal disease (1); schizophrenia (1); Thrombocytopenia (1); Wilms tumor (1).